USP39 (ubiquitin specific peptidase 39)
Diseases named in the same sentence as USP39 in open-access papers (continued):
Sharing a sentence is not in itself a finding about the gene and the disease.
lung carcinoma (continued). "In this study, the expression and role of miR-381 and USP39 in lung cancer were detected to explore whether miR-381 and USP39 can regulate each other and control the reproduction and development of lung cancer cells together." (PMID 36046375, 2022). "In this study, miR-381 mimics could downregulate the expression of USP39 and eventually induce the decrease of the Bcl-2/Bax ratio, control the growth and development of lung cancer cells, and promote the apoptosis of lung cancer cells." (PMID 36046375, 2022). "TargetScan analysis found that miR-381 has specific binding sites with USP39, so it was speculated that USP39 may be a target of miR-381, and USP39 expression can be targeted and regulated by miR-381 to control the development of lung cancer cells." (PMID 36046375, 2022). "As a result, in preclinical and clinical research, USP39 may serve as a potential therapeutic target for the treatment of human lung cancer." (PMID 34502538, 2021). "The results showed that the USP39 mRNA level was significantly increased in lung cancer samples." (PMID 33255748, 2020). "Therefore, the main purpose of this paper is to verify and confirm the function of USP39 in lung cancer cells and to explore novel molecular mechanisms." (PMID 33255748, 2020). "Our study provides experimental evidence for USP39 upregulation in lung cancer." (PMID 33255748, 2020). "Our previous data suggested that USP39 might function as a tumor enhancer in human lung cancer." (PMID 33255748, 2020). "For example, previous studies have demonstrated that USP39 plays a role in carboplatin resistance in ovarian cancer and in regulating chemoresistance to cisplatin by stabilizing CHK2 in human lung cancer cells." (PMID 40990019, 2025). "Therefore, USP39 may serve as a new target for lung cancer treatment." (PMID 36046375, 2022). "Nevertheless, it has been demonstrated that USP39 can regulate the stability of DNA damage-related protein CHK2 by deubiquitination, to further regulate cellular processes in the context of lung cancer." (PMID 33649471, 2021). "Initially, the screen was performed and validated on lung cancer cells whose viability depended on KRAS and subsequently, the top-scoring hit, i.e., USP39, was further validated in CRC cells, given that many of them are also dependent on mut-KRAS signaling." (PMID 34065438, 2021). "In summary, these results suggest that USP39 is highly expressed in NSCLC and may promote the development of lung cancer cells and suggested that USP39 may be a new therapeutic target for NSCLC." (PMID 36046375, 2022). "The expression of USP39 mRNA in lung cancer tissues detected by qRT-PCR was higher than that in the normal control group." (PMID 36046375, 2022). "However, this study also demonstrated downregulated levels of USP39 and CHK2 in lung cancer cells, which may contribute to resistance to radiotherapy treatment in lung cancer tissues." (PMID 38137461, 2023).
ovarian carcinoma (11 papers, 2021 to 2026). A malignant neoplasm originating from the surface ovarian epithelium. "In ovarian carcinoma, a high level of USP39 mRNA and protein was associated with advanced tumor stage, poor OS, and progression-free survival." (PMID 34987596, 2021). "USP39 is overexpressed in ovarian cancer tissues and is closely linked to TNM staging." (PMID 40672756, 2025). "Analyses of the functional effects of USP39 inhibition revealed that this approach significantly suppressed ovarian cancer cell growth and migration, induced cell cycle G2/M phase arrest, and impaired clone formation." (PMID 40990019, 2025). "We analyzed an RNA sequencing dataset from control and USP39 knockdown (KD) human ovarian cancer cells." (PMID 37892157, 2023). "In ovarian cancer, USP39 promotes the proliferation and invasion of cancer cells by facilitating efficient splicing of the oncogenic transcription factor HMGA2." (PMID 35627203, 2022). "In ovarian cancer, it was also reported that USP39 expression is higher in comparison to normal ovarian tissues." (PMID 34577547, 2021). "USP39 was overexpressed and knocked down in ovarian cancer cells using retrovirus and lentivirus infection, respectively." (PMID 33731694, 2021). "Luciferase-expressing ovarian cancer cells with USP39 overexpression or knockdown and control cells were intraperitoneally injected into nude mice (n = 5)." (PMID 33731694, 2021). "Collectively, these findings supported the notion that USP39 exhibits oncogenic potential in the initiation and progression of ovarian cancer." (PMID 33731694, 2021). "Taken together, these data suggested that USP39 is a direct transcriptional target of c-MYC in ovarian cancer cells." (PMID 33731694, 2021). "USP39 knockdown in two ovarian cancer cell lines (HO-8910 and SKOV3) led to inhibition of cell migration and blockage of epithelial-to-mesenchymal transition." (PMID 34577547, 2021). "As a result, phosphorylated SF3B1 was upregulated in ovarian cancer cells with USP39 overexpression and was downregulated in those with USP39 depletion." (PMID 33731694, 2021). "Taken together, our results indicate that USP39 functions as an oncogenic splicing factor in ovarian cancer and represents a potential target for ovarian cancer therapy." (PMID 33731694, 2021). "Consistent with this, ectopic expression of USP39 also significantly enhanced the proliferation of ovarian cancer cells as measured by growth curve and EdU assays." (PMID 33731694, 2021). "Our study highlights the biological significance of USP39 in ovarian cancer development and identifies USP39-modulated splicing events relevant to ovarian cancer pathogenesis." (PMID 33731694, 2021). "Subsequent functional experiments revealed that USP39 promoted the proliferation and invasion of ovarian cancer cells in vitro and tumor growth in vivo." (PMID 33731694, 2021). "We first measured HMGA2 expression in A2780 and CAOV3 ovarian cancer cell lines with USP39 knockdown and in A2780 cells with USP39 overexpression." (PMID 33731694, 2021). "In addition, in the study of tumor drug resistance, the overexpression of USP39 can increase the resistance of colorectal and ovarian cancer cells to chemotherapeutic drugs; this resistance can be reversed by knocking down USP39 expression." (PMID 40672756, 2025). "In addition, USP39 has been reported to be increased in ovarian cancer as compared to normal tissue, with a positive relationship between levels and TNM stage, implying a possible role in disease prognosis." (PMID 39430244, 2024). "Our work also provides evidence for the upregulation of USP39 in ovarian cancer." (PMID 33731694, 2021).
ovarian carcinoma (continued). "In addition, a transwell invasion assay revealed that forced expression of USP39 significantly enhanced the invasion capacity whereas knockdown of USP39 decreased the invasion potential of ovarian cancer cells." (PMID 33731694, 2021). "USP39 was seen to be overexpressed in ovarian cancer tissues in comparison to normal tissues." (PMID 34577547, 2021). "Importantly, USP39 was transcriptionally activated by the oncogene protein c-MYC in ovarian cancer cells." (PMID 33731694, 2021). "We further confirmed the function of USP39 in ovarian cancer tumorigenesis and progression in vivo." (PMID 33731694, 2021). "We then measured USP39 expression in ovarian cancer cells with c-MYC overexpression or knockdown." (PMID 33731694, 2021). "Notably, c-MYC contributes to the regulation of USP39 transcription in ovarian cancer." (PMID 33731694, 2021). "Mechanistically, splicing factor USP39 promoted exon 2 inclusion, thus facilitating the generation of oncogenic BCS1L-L and, thereby, maintaining mitochondrial homeostasis and survival of ovarian cancer cells." (PMID 41771836, 2026). "USP39 promotes efficient splicing of the oncogenic transcription factor HMGA2 at 5’ and 3’ splice sites and increases the malignancy of ovarian cancer cells." (PMID 40990019, 2025). "In ovarian cancer cells HO-8910 and SKOV3, USP39 silencing led to a reduction in cell proliferation in vitro." (PMID 34577547, 2021). "In particular, USP39 facilitates efficient splicing of HMGA2 and thereby increases the malignancy of ovarian cancer cells." (PMID 33731694, 2021). "To evaluate the clinical significance of USP39 in HGSOC, we performed immunohistochemistry using a TMA containing 149 ovarian cancer tissue samples." (PMID 33731694, 2021). "Combined analysis of RIP-seq and RNA-seq data, we identified USP39 facilitates efficient splicing of HMGA2 and that USP39 exerts oncogenic potential partially through regulating HMGA2 in ovarian cancer cells." (PMID 33731694, 2021). "USP39 promotes EMT through beta-collagen signaling and regulates ovarian cancer." (PMID 40990019, 2025). "Moreover, USP39 was found to be overexpressed in high-grade serous ovarian carcinoma (HGSOC) and promotes ovarian cancer malignancy, thereby involved in the poor prognosis of patients with HGSOC." (PMID 35027535, 2022). "To test whether USP39 modulate spliceosome activity via SF3B1, we measured phosphorylated SF3B1 in ovarian cancer cells with USP39 overexpression or knockdown." (PMID 33731694, 2021).
prostate carcinoma (10 papers, 2015 to 2025). A carcinoma that arises from epithelial cells of the prostate gland. "Additionally, they have shown that mutation of newly identified SUMO modification sites of USP39 further promotes the proliferation-enhancing effect of USP39 on prostate cancer cells." (PMID 33572160, 2021). "USP39 is aberrantly expressed in prostate cancer tissues and cells and plays a role as a pro-tumorigenic factor in the malignant progression of prostate cancer." (PMID 40672756, 2025). "Changes in these proteins were found related to myeloid malignancy (u2af2), clinical monoclonal B-cell lymphocytosis (sf3b1), and prostate cancer (usp39)." (PMID 32823483, 2020). "In patients with prostate cancer, high expression of USP39 predicts poor prognosis and USP39 promotes tumorigenesis of prostate cancer cells via promoting EGFR mRNA maturation and transcription elongation." (PMID 30898977, 2019). "Of interest, the first two and the last two exons of USP39 showed up-regulation but exons 4–10 demonstrated down-regulation in prostate cancer." (PMID 26979803, 2016). "The effective regulation of EGFR pre-mRNA splicing function by USP39 suggests that it may have the potential to become a target for targeted therapy of prostate cancer." (PMID 40672756, 2025). "It is noteworthy that prostate cancer cell proliferation is inhibited when SUMO binds to sites on USP39, but the attraction phenomenon can be reversed when these SUMO binding sites are mutated, suggesting that SUMO modification can inhibit the tumor-promoting effects of USP39." (PMID 40672756, 2025). "Inhibition of human ubiquitin specific peptidase 39 (USP39) SUMOylation promotes the USP39-enhanced proliferation of prostate cancer cells, and the inhibition of methyl methane sulfonate ultraviolet sensitive gene clone 81 (MUS81) SUMOylation can contribute to tumorigenesis." (PMID 35408841, 2022). "It was found in our previous study that USP39 knockdown could inhibit the abnormal proliferation of prostate cancer cells by inhibiting the splicing maturation and transcriptional prolongation of EGFR mRNA." (PMID 34544400, 2021). "Moreover, overexpression of USP39 predicts poor prognosis and promotes tumorigenesis of prostate cancer via promoting epidermal growth factor receptor (EGFR) mRNA maturation and transcription elongation." (PMID 30898977, 2019). "Mutation of above lysine residues could eliminate these original sumoylation sites of USP39 and further promoted the proliferation-enhancing effect of USP39 on prostate cancer cells." (PMID 26154679, 2015). "Univariate analysis indicated that high USP39 expression (Hazard ratio (HR) = 2.167,P<0.025), Gleason score>7 (HR=1.966, P=0.001), high PSA (HR=1.925, P=0.048) and capsular invasion (HR = 6.821, P=0.008) were independent risk factors for BCR of prostate cancer patients." (PMID 26959883, 2016). "Then, we used ROC curve to analyze the predictive ability of Gleason score and USP39 for BCR and found that Gleason score and USP39 could be used as prognostic factors for BCR of prostate cancer." (PMID 26959883, 2016).
glioma (9 papers, 2019 to 2025). A benign or malignant brain and spinal cord tumor that arises from glial cells (astrocytes, oligodendrocytes, ependymal cells). "We found that high USP39 expression was positively associated with poor prognosis of glioma patients." (PMID 33811456, 2022). "We found increased protein levels of USP39 to be associated with higher tumor grade in an independent cohort of primary human gliomas." (PMID 31332287, 2019). "In patients with gliomas, high USP39 expression is associated with a poor prognosis." (PMID 40990019, 2025). "Additionally, overexpression of ADAM9 inhibited the migration and invasion of glioma cells caused by USP39 depletion in vitro." (PMID 33811456, 2022). "Finally, loss of USP39 decreased TAZ pre-mRNA splicing efficiency in glioma cells in vitro, which led to reduced levels of TAZ protein." (PMID 31332287, 2019). "To explore the potential mechanisms underlying USP39-induced malignant behaviors in glioma, we transfected a series of luciferase reporter constructs to assay signaling activity from seven different pathways, such as Notch, Hippo, and Wnt, which are typically dysregulated in human cancers." (PMID 31332287, 2019). "Interestingly, patients with glioma have a higher risk of developing depression, suggesting that USP39 may serve as a potential bridge between the two conditions." (PMID 38020762, 2023). "We verified that USP39 expression was associated with tumor grade, independent from other clinicopathological factors, including age, gender, tumor size, cystic change, and edema, which suggested that USP39 could be a potential diagnostic factor for glioma patients (p < 0.05)." (PMID 31332287, 2019). "USP39 regulates TAZ protein expression by inducing TAZ mRNA maturation and exerts USP39 oncogenic properties in glioma." (PMID 40990019, 2025). "USP39 stabilizes Cyclin B1 expression by deubiquitinating it and promotes G2/M cell cycle transition and glioma cells proliferation." (PMID 40990019, 2025). "In contrast to PD, MDD astrocytes exhibit higher expression levels of the Ubiquitin specific protease 39 (USP39) gene, which has oncogenic effects and plays a role in various cancers, including promoting glioma progression." (PMID 38020762, 2023). "Our study shows that ubiquitin‐specific protease 39 (USP39) is highly expressed in human glioma and the high USP39 expression significantly correlated with poor overall survival in patients with glioma." (PMID 33811456, 2022). "TMA of 63 human gliomas were analyzed to further confirm the expression correlation of USP39/ADAM9 axis." (PMID 33811456, 2022). "To further validate the function of USP39 in the development of human glioma, we constructed a USP39 expression plasmid and transfected it into glioma cells." (PMID 33811456, 2022). "Taken together, these results suggested that high USP39 expression was positively correlated with the occurrence of glioma." (PMID 33811456, 2022). "To detect the role of USP39 in the development of glioma, we knocked down the expression of USP39 in glioma cells with siRNA." (PMID 33811456, 2022). "In the present study, we identified an oncogenic role for USP39 in human glioma and confirmed its function in the migration and invasion of glioma." (PMID 33811456, 2022). "The results exhibited that most of the genes of tri‐snRNP were positively correlated with USP39 in the glioma samples and upregulated in the USP39‐overexpressing U87 cells, indicating that USP39 plays a vital role in the tri‐snRNP complex." (PMID 33811456, 2022). "Then, we analyzed the expression levels of the eight downregulated genes following USP39 knockdown, and the correlation between their expression and USP39 expression in TCGA glioma samples." (PMID 33811456, 2022). "In this study, we analyzed USP39 expression in human glioma samples from the Oncomine database and its correlation with patient survival." (PMID 33811456, 2022).